IL17A (interleukin 17A)
Diseases named in the same sentence as IL17A in open-access papers (continued):
Sharing a sentence is not in itself a finding about the gene and the disease.
periodontitis (continued). "Various inflammatory mediators, such as IL-6, IL-17A and MMP-8, are essentially involved in the pathogenesis of both PCOS and periodontitis, and especially, the expression and release of MMP-8 increase significantly during the aggravation of periodontal inflammation and the resultant destruction." (PMID 37794378, 2023). "in the oral microbiota of patients with periodontitis and OSA might well be responsible for the high levels of IL-17A and IL-33 in GCF, worsening periodontal disease." (PMID 36967976, 2023). "Additionally, higher levels of IL-6, IL-17A and IL-33 were detected in the saliva of SLE patients with chronic periodontitis." (PMID 36949458, 2023). "Periodontitis is a common chronic inflammatory disease that is characterized by disordered glucose metabolism and the cytokines: interleukin-1 (IL-1), interleukin-6 (IL-6), tumor necrosis factor-α (TNF-α), and interleukin-17A (IL-17A)." (PMID 38098816, 2023). "Compared to healthy individuals, periodontitis patients have a decreased expression level of Treg cell-related gene Foxp3 and increased levels of Th17 cell-related genes RAR-related orphan receptor C (Rorc) and IL-17A." (PMID 35222410, 2022). "Similar to IL-17A, IFN-γ is also increased in periodontitis patients." (PMID 34381457, 2021). "Furthermore, an increased number of IL‐17A+ cells and decreased Foxp3+ cells per bone surface were observed in OVX/periodontitis rats and this skewed CD4+ T cell‐mediated osteoimmune response was rescued by the administration of probiotics." (PMID 34101283, 2021). "The increasing trend of salivary IL-17A levels in subjects with periodontitis compared to those without periodontitis in both the control and the type 2 DM groups are demonstrated in our study." (PMID 32053656, 2020). "Human data on serum and salivary IL-17A and IL-18 in patients with DM with and without periodontitis are, however, still sparse." (PMID 32053656, 2020). "Salivary IL-17A levels were not significantly different between patients with DM and controls, however, the levels were significantly higher in controls with periodontitis than those without periodontitis (p = 0.031)." (PMID 32053656, 2020). "Whole salivary IL-17A and IL-23 levels were significantly higher among cigarette-smokers compared with non-smokers with periodontitis (p < 0.01) and periodontally-healthy individuals (p < 0.01)." (PMID 33066031, 2020). "Whole salivary IL-17A and IL-23 levels were significantly higher in marijuana-smokers compared with cigarette-smokers (p < 0.01) and non-smokers with periodontitis (p < 0.01)." (PMID 33066031, 2020). "Whole salivary IL-17A and IL-23 levels were higher among cigarette-smokers than non-smokers with periodontitis (p < 0.01) and periodontally-healthy-individuals (p < 0.01)." (PMID 33066031, 2020). "Results showed that in this environment of persistent dysbiosis as occurs in periodontitis, the CD4+ T lymphocyte-mediated immune response evolves from one initially dominated by IL-17A to one that is predominantly IFN-γ-producing, in a response generated de novo by Th1 cells." (PMID 33363538, 2020). "There was a trend of higher levels of salivary IL-17A in the type 2 DM subjects with periodontitis (DM-P group) than that of the type 2 DM subjects without periodontitis (DM-NP group) but no statistical significance was revealed (p > 0.05)." (PMID 32053656, 2020). "Salivary IL-17A and IL-23 levels were higher in marijuana-smokers than cigarette-smokers (p < 0.01) and non-smokers-with-periodontitis (p < 0.01)." (PMID 33066031, 2020). "Additionally, there are no studies comparing the levels of cytokines in saliva and GCF in individuals with periodontitis and OSA, to individuals who only have periodontitis or OSA, therefore it is unknown what function IL-17A plays in OSA patients." (PMID 36967976, 2023).
periodontitis (continued). "IL-17A can promote keratinocytes to secrete antimicrobial peptides and play a defensive role, but whether it plays a role in the progression of periodontitis has not been confirmed." (PMID 35371044, 2022). "The treatment of PsO with IL-17A inhibitors may also significantly slow down the occurrence and development of periodontitis, but there is still a lack of research evidence." (PMID 35371044, 2022). "In addition, IL-17A can also act synergistically with IL-1 and TNF-α to induce gingival fibroblasts to produce MMP-1 and MMP-3, which plays an important role in the tissue destruction in periodontitis." (PMID 35371044, 2022). "At present, there are no clinical studies on IL-17A inhibitors for the treatment of periodontitis." (PMID 35371044, 2022). "The concentration of IL-17A in the serum of periodontitis patients with osteoporosis was significantly higher than that of periodontitis patients without systemic diseases, suggesting that IL-17A may be related to the progression of osteoporosis." (PMID 35371044, 2022). "For example, anti-IL-17A antibody alone could not alleviate periodontitis because of the concomitant rise in GM-CSF." (PMID 34557201, 2021). "However, when the periodontal status was taken into account, significantly higher salivary IL-17A levels in the control subjects with periodontitis (C-P group) compared to those without periodontitis (C-NP group) (p = 0.031) was observed." (PMID 32053656, 2020). "This suggests that, neutrophils are not a source IL-17A in our periodontitis model." (PMID 32391008, 2020). "We next measured serum IL-17A levels and found that serum IL-17A levels were not significantly different between the DM group and the control group or between those with and without periodontitis." (PMID 32053656, 2020). "We observed that the IL17A 197AA genotype was more frequent in patients with chronic periodontitis (CP), females with CP, and the Caucasian and nonsmoking Caucasian patients with CP than in respective controls, and this could be correlated to the risk of disease." (PMID 26339129, 2015). "As a result, the study’s aim was to investigate the levels of salivary IL-17A, IL-18, and IL-1B in celiac disease patients on GFD with and without periodontitis compared to healthy controls." (PMID 38756445, 2024). "IL-17A has not previously been measured in saliva of BD or RAS patients, but has been investigated in chronic periodontitis in which it was significantly lower than HC." (PMID 35003055, 2021). "The present results showed that whole salivary IL-17A and IL-23 levels were significantly higher in the UWS of marijuana-smokers compared with non-smokers with periodontitis." (PMID 33066031, 2020). "In particular, we hypothesized that the GCF levels of RANKL, OPG, IL-6, IL-17A, and MMP-8 do not change during this orthodontic treatment and are lower than those detected during periodontitis." (PMID 36902236, 2023). "In the present study, the levels of different pro-inflammatory and pro-destructive mediators common between periodontitis and orthodontics were quantified, and it was shown that the levels of the RANKL, OPG, IL-6, IL-17A, and MMP-8 do not vary during the 2 years of orthodontic treatment." (PMID 36902236, 2023). "A small population of IL-17A+FOXP3+ cells were found in periodontitis, but not in gingivitis, suggesting the functional plasticity of Treg cells transforming into inflammatory Th17 cells in the periodontitis environment." (PMID 34177907, 2021). "Of particular interest, in periodontitis patients, IL-36γ mRNA is positively correlated with archetypal inflammatory cytokines already known to be involved in periodontitis and inflammatory diseases, i.e., IL-1β, IL-6, TNF-α and IL-17A while IL-36β or IL-36Ra are not correlated with these cytokines." (PMID 31848404, 2019).
multiple sclerosis (347 papers, 2008 to 2026). A progressive autoimmune disorder affecting the central nervous system resulting in demyelination. "Tfh17 cells are defined by IL-17A production and are associated with inflammatory autoimmune diseases such as multiple sclerosis (MS) and RA." (PMID 40283219, 2025). "Bacterial species that were more abundant in cases with disease-active treatment-naïve multiple sclerosis were positively linked to a group of plasma cytokines including IL-22, IL-17A, IFN-β, IL-33, and TNF-α." (PMID 36604748, 2023). "We demonstrate an aberrant bacterial and viral gut microbiota in multiple sclerosis and that an IL-17A-linked bacterial gut microbiota increases with disease activity." (PMID 36604748, 2023). "Multiple sclerosis and susceptibility to cardiovascular diseases: Implications of ethnicity-related interleukin-17A gene polymorphism?" (PMID 27648032, 2016). "IL-17A as a Th17 cytokine plays a pathogenic role in CNS-related inflammation, such as multiple sclerosis." (PMID 24367714, 2013). "Experimental autoimmune encephalomyelitis (EAE) is a mouse model of multiple sclerosis that is associated with the production of IL-17A." (PMID 22768117, 2012). "Prkca is a Th17 cell–selective kinase regulating IL-17A production and acts as a tumor suppressor in the intestine; reduced expression is associated with other immune-mediated phenotypes, including multiple sclerosis." (PMID 32897876, 2020). "IL-10+ CD4+ T cells co-expressing IFN-γ or IL-17A have also been described in the affected tissues of animal models of multiple sclerosis and uveitis." (PMID 40433375, 2025). "On the other hand, IL-17A plays a key role in chronic pathologies such as multiple sclerosis, where it contributes to neuronal degeneration via inflammation." (PMID 41010614, 2025). "In multiple sclerosis, IL-17A plays a role in disrupting the blood–brain barrier and recruiting immune cells to the central nervous system, exacerbating neural damage." (PMID 38892253, 2024). "During experimental autoimmune encephalomyelitis (EAE), a mouse model of multiple sclerosis, IL-17A plays a pivotal role." (PMID 36857006, 2023). "In diseases that affect the CNS, the level of IL-17A increases in the CSF and peripheral blood in multiple sclerosis." (PMID 38098004, 2023). "A cluster of inflammation markers composed of blood leukocytes, CRP, and blood cell gene expression of IL17A and IL6 was positively associated with a cluster of multiple sclerosis-related species." (PMID 36604748, 2023). "Modulation of the gut microbiota of mice by oral gavage of Lactobacillus reuteri protected mice from multiple sclerosis-like disease symptoms by decreasing IL-17A levels." (PMID 36543914, 2022). "GRIM-19 ameliorates multiple sclerosis through reciprocal regulation of IFNγ/Th1 and IL-17A/Th17 cells in a mouse model of experimental autoimmune encephalomyelitis." (PMID 36387896, 2022). "Preliminary trials of anti–IL-17A biologics in multiple sclerosis have shown some promising hints of efficacy, although this cytokine is certainly not the sole factor driving pathogenesis." (PMID 34914635, 2022). "IL-17A is well recognized for its effects in neurological disorders, including multiple sclerosis (MS), Alzheimer’s disease (AD), Parkinson’s disease (PD), and ischemic brain injury, and more recently with the development of anxiety and depression." (PMID 35216112, 2022). "Interleukin-17A produced mainly by specialised T cells, Th17 and γδ T cells, plays a role in acute brain ischaemia, stroke and multiple sclerosis." (PMID 35130911, 2022). "Vitamin D3 supplementation was found to improve multiple sclerosis by downregulation of both IL17A and IL6 levels." (PMID 36233290, 2022). "IL-17A is a pro-inflammatory cytokine that is involved in neuroinflammatory and neuropsychiatric disorders such as autism, depression, and multiple sclerosis." (PMID 36248001, 2022).
multiple sclerosis (continued). "For example, secukinumab, anti-IL-17A antibody, was tested in relapsing multiple sclerosis patients (NCT01874340) and has been tested in psoriatic arthritis (NCT04711902) or lupus nephritis (NCT04181762)." (PMID 34745114, 2021). "MOG-reactive Th17 cells are known to induce autoimmune neuroinflammation, and IL-17A has been proposed as a promising target for the treatment of multiple sclerosis (MS)." (PMID 31936879, 2020). "There is a close connection between IL-17A expression and the pathogenesis of CNS inflammatory diseases, including depression, ischaemic brain injury and multiple sclerosis." (PMID 30501622, 2018). "There is a convincing body of evidence that IL-17A plays an important role in inflammatory brain disorders including multiple sclerosis, infectious CNS diseases and stroke as well as in the pathophysiology of vascular inflammation and arteriosclerosis." (PMID 23468966, 2013). "To assess the in vivo relevance of the pro-Th17 effect of PGI2 analogs, we used WT and IP KO mice in a mouse model of human multiple sclerosis, EAE, a disease associated with IL-17A as IL-17A is important for the early phase of EAE development." (PMID 22590492, 2012). "The IL-17a cytokine family has been proposed to play a crucial role in human inflammatory, autoimmune and neurodegenerative diseases, including Alzheimer’s disease, Parkinson’s disease and multiple sclerosis, likely by activating glial cells." (PMID 39466030, 2024). "However, the anti–IL-17A therapeutic antibody secukinumab was shown to decrease the development of new lesions in a small, double-blind clinical trial of patients with multiple sclerosis." (PMID 38686385, 2024). "In addition, we observed a reduced production of IL-17A, a proinflammatory cytokine that plays a pivotal role in multiple sclerosis, only in the mice that had been treated with the PS-LNPMOG." (PMID 37765078, 2023). "Interleukin-17A is associated with TBI severity and also progression in multiple sclerosis." (PMID 35130911, 2022). "In addition to cells in the peripheral immune system, microglia was also a cell type that responds to IL-17A through the NF-κB pathway during neuroinflammation, such as multiple sclerosis." (PMID 34979902, 2022). "D. Contrary to our finding an experimental study on healthy human donor using CD4+ T cells and mouse model for multiple sclerosis showed that 1,25(OH)2D3 inhibits human IL-17A and suppresses mouse IL-17A; other studies in mice imply this regulatory effect on Th17 cells by Vit." (PMID 26504859, 2015). "IL-17A has been determined to be involved in neurodegenerative diseases such as multiple sclerosis." (PMID 26373740, 2015). "MiR-326 plays a role in multiple sclerosis models, influencing the IL-17A expression." (PMID 24692846, 2014). "In addition, IL-17A has been shown to play an important role in various autoimmune neuroinflammatory diseases such as multiple sclerosis (MS) and experimental autoimmune encephalomyelitis (EAE)." (PMID 22748016, 2012). "Furthermore, IL-17a has been linked to inducible nitric oxide synthase (iNOS)-mediated neuroinflammation, which has been shown to result in neuronal damage following Zika virus infection, as well as to BBB breakdown in multiple sclerosis." (PMID 39466030, 2024). "Moreover, IL-17F is associated with relapse in multiple sclerosis, and IL-17A does not show that correlation, which is quite different from animal models." (PMID 28210632, 2017). "Th17 cells and IL-17A are involved in BBB destruction in multiple sclerosis (MS) and autoimmune encephalomyelitis (EAE) disease models, and it is reasonable to suspect that IL-17-producing cells also contribute to BBB dysfunction after stroke." (PMID 37884768, 2024). "In Multiple Sclerosis (MS), CBD in preclinical models of MS resulted in a reduction of proinflammatory cytokines such as IL-17A, IFN-γ, TNF-α, IL-6 and IL-1b and an increase in anti-inflammatory cytokines such as IL-4, IL-10 and TGF-β." (PMID 38601151, 2024).
multiple sclerosis (continued). "We have recently reported that CD28 autonomous signaling induces the expression of IL-17A in peripheral CD4+ T lymphocytes from healthy donors, multiple sclerosis, and type 1 diabetes patients." (PMID 31068940, 2019). "For example, psoriatic lesions appear to have upregulation of both IL-17A and IL-17F, while upregulation of IL-17A, but not IL-17F have been noted in multiple sclerosis brain biopsy." (PMID 37115755, 2023). "Peroxisome Proliferator-Activated Receptor-γ (PPAR-γ) agonists inhibit Th17 differentiation in isolated T cells derived from multiple sclerosis and healthy patients by blocking STAT3 and downregulating RORγt, with a subsequent decrease in IL-17A protein production." (PMID 32987705, 2020). "Experimental autoimmune encephalomyelitis, a representative Th17 cell- dependent model of multiple sclerosis, required IL-17A but not the other Th17 cytokines for the disease development." (PMID 29615652, 2018). "Among the cytokines that could not be detected were IFN-γ, IL-17A and tumor necrosis factor (TNF)-α, which have been linked to the pathophysiology of multiple sclerosis." (PMID 36756308, 2023).